SCD (stearoyl-CoA desaturase)
Diseases named in the same sentence as SCD in open-access papers (continued):
Sharing a sentence is not in itself a finding about the gene and the disease.
tumor (continued). "For instance, in tumors driven by c-Myc, the IRE1α/XBP1s axis promotes tumor growth by enhancing the expression of stearoyl-CoA desaturase 1 (SCD1), a critical enzyme involved in lipid metabolism and tumor invasion within the ER." (PMID 40278350, 2025). "The anti-tumor actions of the Stearoyl-CoA desaturase (SCD1) inhibitor aramchol in tumor cells remains poorly understood." (PMID 40827882, 2025). "Quantitative analysis demonstrated significant positive correlation between DUSP9 and SCD protein expression in HCC tumours." (PMID 41383134, 2025). "Consistently, IHC assays confirmed decreased expression of FASN, ACLY, and SCD in tumor tissues derived from VPS72 knockdown cells." (PMID 40305746, 2025). "Consistently, treatment with SCD inhibitors reduced tumor formation in xenograft models of gastric and colon cancer." (PMID 40814339, 2025). "The conversion of saturated fatty acids to unsaturated fatty acids by SCD provides energy that boosts proliferation and reduces oxidative stress, thereby promoting tumor progression." (PMID 39543650, 2024). "Recently, it was shown that elevated levels of SCD protect tumor cells against programmed cell death and ferroptosis (see also below)." (PMID 39337514, 2024). "SCD promotes ATP production, which provides the necessary conditions for rapid tumor growth and metastasis initiation." (PMID 39103344, 2024). "Integration of comprehensive tumor immunological and genomic data revealed a robust positive correlation between SCD expression levels and the abundance of CD8+ T cells and macrophages." (PMID 39351232, 2024). "Lastly, the IGF2BP3 knockdown restrained CC growth and lipid metabolism, after which SCD overexpression rescued the influence in vitro and in vivo using nude mouse tumor-bearing model." (PMID 38355626, 2024). "Overall, robust tumor-suppressive effects were achieved in vivo by increasing tumor stearate levels via S-HFD feeding coupled with oleate inhibition mediated by SCD inhibition." (PMID 39617788, 2024). "In contrast, the central tumor area showed an increased activity in hypoxic response and cholesterol homeostasis pathways, putatively driven by the upregulation of genes like SCD." (PMID 38200223, 2024). "Our research aligns with other studies that have identified a significant correlation between high SCD expression and an unfavorable prognosis in various tumor types." (PMID 39351232, 2024). "SCD has been extensively studied for its role in promoting tumor initiation, progression, metastasis, and stemness." (PMID 39351232, 2024). "MF-438 combined with a MAPK inhibitor effectively reduced tumor drug resistance MK-8245 is a potent liver-targeted SCD inhibitor with antidiabetic and antidyslipidemic effects." (PMID 38302980, 2024). "Overall, this study provides an in-depth understanding of the heterogeneity and complexity of the molecular biological characteristics of SCD and FADS2 by analyzing the prognosis, mutations, and tumor immune microenvironment in BRCA." (PMID 38905386, 2024). "We saw that the injection of Hela cells expressing shIGF2BP3+oe-NC reduced significantly the tumor size than those of shNC cells, however mice injected with shIGF2BP3+oe-SCD-expressing hela cells had slightly increased tumors." (PMID 38355626, 2024). "The deletion of SCD did not affect tumour growth, but it selectively decreased the levels of the SCD-derived MUFAs oleic, palmitoleic and vaccenic acids in the tumour interstitial fluid." (PMID 39433871, 2024). "Next, IHC staining of mouse tumor tissue using the SCD antibody showed that SCD expression diminished following IGF2BP3 knockdown." (PMID 38355626, 2024). "Herein, we identified SULT2B1 as a novel metastasizing tumour marker for CC, which promoted lipid metabolism and metastasis capacity of CC cells by directly interacting with stearoyl‐CoA desaturase (SCD1)." (PMID 38372484, 2024).
tumor (continued). "The 12-HHTrE-LTB4R2 pathway revealed by our study is a mode of SCD-dependent PUFA reprogramming in aHSC which has tumor-promoting paracrine effects likely involving similar reprogramming in tumor cells and other TME cell types." (PMID 37156770, 2023). "In the IKE-treated group, CREB1 knockdown reduced the tumor volume and weight, and this effect was reversed by SCD overexpression." (PMID 37957645, 2023). "Relatedly, we also examined expression levels of known LXR target genes and found that SREBP1c, ACC, and SCD transcript levels were elevated in the tumor tissues, while ABCA1 levels were decreased." (PMID 36830714, 2023). "Upregulated SCD further promotes tumor growth by decreasing ER stress and increasing the levels of phosphorylated AKT and other pathways." (PMID 36472914, 2023). "The critical role of DNL enzymes in regulating tumorigenesis has been shown through genetic evidence from several studies including the knockdown of ACLY, ACC, FAS, and SCD in various tumor types." (PMID 37958642, 2023). "WB analysis further confirmed that tumor tissues with circZBTB46 knockdown had lower expressions of SCD protein than the sh-NC group." (PMID 36672408, 2023). "This is consistent with a recent study that demonstrated that low-glycemic diets inhibit PDAC tumor growth by suppressing the activity of SCD and decreasing MUFA levels in tumor cells." (PMID 37069167, 2023). "SCD is a key gene in the biosynthesis of unsaturated FA, and it was found to be significantly up-regulated in serrated lesion and tumor tissue." (PMID 37164975, 2023). "As a result, the expression of SCD, a PPARα/γ target gene involved in tumor progression and chemoresistance, was significantly downregulated." (PMID 36472914, 2023). "SCD requires oxygen to catalyze the desaturation reaction, so less unsaturated FAs are found in hypoxic conditions, resulting in decreased tumor cell viability." (PMID 37046804, 2023). "SCD is highly expressed in tumor tissues (Fig. 4f2), while FADS is more expressed in lymphoid tissues (Fig. 4f3, g3)." (PMID 37164975, 2023). "For instance, altering the KD fat composition, by using palm oil instead of lard as the source of fat, slowed tumor growth, by increasing tumor saturated fatty acid levels, lowering MUFAs and decreasing tumor stearoyl-CoA desaturase activity." (PMID 36382086, 2022). "SCD supports lipogenesis and desaturation of tumor cells under the reduced supply of exogenous lipids, which is important for cell viability and proliferation of tumors." (PMID 35896782, 2022). "Sodium selenite treatment upregulated pro-apoptotic, apoptotic, and tumor suppressor genes such as ATF3, FOSB, GADD45B, DUSP8 and ACHE, and downregulated tumor cell survival genes such as SCD, LRP1, RAB31, SRPX2, PDK1 and CSGALNACT1." (PMID 36059619, 2022). "We recall that the enrichment of oleic acid in membrane phospholipids is an important biomarker of SCD-1 activation and tumor proliferation, whereas SCD-1 inhibition is obtained by exogenous supplementation of oleic acid." (PMID 35053341, 2022). "A recent study from the Massachusetts Institute of Technology found that reducing SCD enzyme activity in tumor cells or adopting a low-fat diet (especially unsaturated fatty acids) can affect tumor growth." (PMID 36588702, 2022). "All these results suggest that CAF-derived and exogenous lipids can compensate for low SCD expression and then alter lipid composition, further influencing cell membrane fluidity, which plays a profound role in promoting tumor growth and metastasis." (PMID 35342344, 2022). "Despite a modest ECF to plasma ratio (6.4% of plasma), the SCD inhibitor showed significant therapeutic effects on tumor growth and survival in all three models." (PMID 33568479, 2021). "We have previously shown that SCD-1 expression correlates with other cellular markers of the tumor hypoxic microenvironment, such as EPO, EPO-R, VEGF and VEGF-R in ccRCC." (PMID 34199164, 2021).
tumor (continued). "Despite the potential of SCD inhibitors to reach the clinic, we know little about tumor cell resistance to such therapy." (PMID 33568479, 2021). "Previous studies have demonstrated the overexpression of enzymes associated with lipid metabolism, including stearoyl-CoA desaturase-1 (SCD-1), which increases the concentration of unsaturated fatty acids in tumor cells." (PMID 34199164, 2021). "In this work, we studied the expression of SCD-1 in primary ccRCC tumors, as well as in cell lines, to determine its influence on the tumor lipid composition and its role in cell proliferation." (PMID 34199164, 2021). "The lipogenic enzyme stearoyl CoA desaturase (SCD) plays a key role in tumor lipid metabolism and membrane architecture." (PMID 33568479, 2021). "Inhibitors targeting SCD have been shown to induce the apoptosis of tumor cells and to inhibit tumor formation in a xenograft model of gastric cancer." (PMID 34766135, 2021). "Accordingly, FOSB inhibition blunted acquired resistance and extended survival of tumor-bearing mice treated with SCD inhibitor." (PMID 33568479, 2021). "Stearoyl co-A desaturase (SCD) is another key enzyme in FA synthesis and is correlated with oncogenesis, tumor progression, and overall survival." (PMID 34742349, 2021). "We next combined enzalutamide with an inhibitor of Stearoyl CoA Desaturase 1 (SCD1), an important enzyme in DNL, and observed significantly reduced tumor growth caused by the important change in tumoral lipid desaturation." (PMID 33187317, 2020). "Using the B2M gene as reference, the expression of SCD in the peritumoral area was more than 5 times higher (p = 0.005) than in the growing tumor area." (PMID 32392704, 2020). "On other hand, tumor hypoxia constrains oxygen-dependent stearoyl-CoA desaturase (SCD), resulting in an accumulation of saturated FA precursors." (PMID 33364199, 2020). "High expression of SCD was required for tumor development in mice by regulating synthesis of oleate in the enterocytes and by maintaining fatty acid homeostasis." (PMID 33537062, 2020). "For instance, SCD regulates apoptosis in hepatocarcinoma and prostate cells, increases hepatoma cells proliferation, and its inhibition reduces tumor cells’ survival in breast and prostate cancer." (PMID 33050166, 2020). "In this regard, SREBP proteins, which are master regulators of lipid metabolism, together with FASN and SCD have been found to be upregulated in several neoplasias." (PMID 33212825, 2020). "The expression of SCD in GBM was significantly lower in the growing tumor area compared to the peritumoral area and in the necrotic core compared to the peritumoral area." (PMID 32392704, 2020). "In the tumor, the expression of stearoyl–coenzyme A desaturase (SCD) and fatty acid desaturases 2 (FADS2) was lower than in the peritumoral area." (PMID 32392704, 2020). "Especially, the candidates ABCA1, MET, and SCD were entangled with tumor metabolism, while FCGR1A and ITGB2 showed the widest interactions with immunological processes." (PMID 32228647, 2020). "Fatty acid desaturation, which requires molecular oxygen, is inhibited in hypoxic tumor regions (SCD and FADS2)." (PMID 32103057, 2020). "Regarding CRC, SCD is able to promote tumor cell proliferation and inhibit apoptosis, besides augmenting metastasis through MUFA increased production." (PMID 33050166, 2020). "Using the GAPDH gene as reference, in the peritumoral area, we observed a significantly higher (almost 4 times) expression of SCD than in the growing tumor area (p = 0.015) and almost 3 times higher expression than in necrotic core (p = 0.019)." (PMID 32392704, 2020). "By performing gene‐level studies in tumour cells, we identified the central role of SCD in the mechanisms of cell replication." (PMID 30592142, 2019). "The results of immunohistochemistry and western blotting staining all suggested a significant elevation of SCD gene expression in tumour tissues compared to that in adjacent normal bladder mucosal tissues." (PMID 30592142, 2019).
tumor (continued). "To confirm that DNFA enzyme inhibition is the crucial driver for reduced cell viability, we then used small molecule inhibitors of FASN and SCD enzymes, which reportedly decreased tumor growth in preclinical studies." (PMID 31316083, 2019). "Not surprisingly, compared with that of the normal tissues, the SCD mRNA level was significantly elevated in tumours." (PMID 30592142, 2019). "More evidence suggests that SCD modulates the replication rate of tumour cells by regulating certain factors in cell cycle progression." (PMID 30592142, 2019). "Subsequently, a series of researches showed that SCD inhibition has anti‐proliferative and apoptosis effects in a variety of neoplasm cells." (PMID 30592142, 2019). "In this regard, SREBP proteins, which are master regulators of lipid metabolism, together with FASN and SCD have been found to be upregulated in several neoplasia." (PMID 30913248, 2019). "Next, to verify this result, we tested the mRNA level of SCD in 25 paired and 91 unpaired normal bladder mucosal and/or tumour tissue specimens by real‐time PCR." (PMID 30592142, 2019). "We also found that the membrane fluidity regulating enzyme stearoyl-CoA desaturase 1 (SCD1) was upregulated in tumor cells co-cultured with CAFs and established its essential role for both intrinsic and CAF-driven tumor cell motility." (PMID 29849946, 2018). "Although clearly important for cell survival, activity of the oxygen (O2)-dependent SCD enzyme can be constrained by tumor hypoxia." (PMID 30184495, 2018). "Stearoyl-coenzyme A (CoA) desaturase (SCD), the principal enzyme responsible for desaturation, is critical for sustained viability of a variety of tumor cell types." (PMID 30184495, 2018). "Oleate (C18:1), another end product of SCD, also had tumor-promoting roles in HCC by phosphatase and tensin homolog deleted on chromosome 10 (PTEN) downregulation via mTOR/NF-κB-mediated upregulation of microRNA-21." (PMID 30445800, 2018). "Of importance, tumor cells that acquire lipids through extracellular scavenging are resistant to stearoyl-CoA desaturase 1 (SCD1) inhibitors." (PMID 29093815, 2017). "We also found that expression of SCD increased with tumour grade and was higher in patients with low overall survival." (PMID 27042297, 2016). "As the SCD reaction requires molecular oxygen, it is likely that lipid desaturation is affected by tumour hypoxia." (PMID 27042297, 2016). "In order to investigate the effect of SCD inhibition on established tumours, a second cohort was treated with doxycycline starting at day 47 post-implantation (late)." (PMID 27042297, 2016). "In our study, CDH1 was one of seven EMT-associated genes (CDH1, SCD, PAPSS2, C3orf52, FREM, SLC22A24, SLC25A29) successfully validated to be deregulated in tumor tissue." (PMID 27549611, 2016). "In the early treatment regimen, SCD ablation resulted in a substantial attenuation in tumour growth, while tumours in the untreated cohort, or the doxycycline-treated mice implanted with DU145 cells expressing non-targeting controls, continued to expand." (PMID 27042297, 2016). "SCD expression also determined reduced progression-free survival of high-grade tumours and those stratified by the PAM50 gene expression signature, which defines basal-like aggressive disease that presently has limited therapeutic options." (PMID 27042297, 2016). "This excludes potential effects on desaturase activity in cells of the tumour stroma or global alterations in the lipid metabolism of the host, which can contribute to tumour inhibition by systemic SCD inhibition." (PMID 27042297, 2016). "Inhibition of stearoyl-CoA desaturase 1 (SCD1) has been found to effectively suppress tumor cell proliferation and induce apoptosis in numerous neoplastic lesions." (PMID 26813308, 2016). "Recent reports on the modulation of SREBP1 and/or SCD in tumor models support the potential of this strategy." (PMID 26061814, 2015).
tumor (continued). "For instance, the average ratio of 18:1 to 18: 0 in the CE pool was 3.92 in the wild-type liver and increased to 11.59 in AKT/Ras tumor CE pool, consistent with the increased stearoyl-CoA desaturase activity in the tumor tissues." (PMID 24069385, 2013). "The requirement for SCD in tumor initiation and progression as well as the role of SCD in mediation AKT/mTOR induced tumor cell proliferation have not been tested using genetic models, such as SCD1 null mice, to date." (PMID 24069385, 2013). "Ketogenic diet (KD) may influence tumor progression by regulating lipid metabolism.While KD damages tumor SCD activity, the increased lipid availability driven by KD maintains the ratio of unsaturated fatty acids to SFAs in the tumor." (PMID 41421797, 2025). "Similarly, the study highlighted the role of SCD in tumor metabolism, noting its reduced expression in tumor regions compared to peritumoral areas." (PMID 40430008, 2025). "Furthermore, lipid accumulation in the tumor microenvironment suppresses T-cell function via palmitoylation of PD-L1, and the activity of FASN/SCD is intricately linked to membrane lipid synthesis and signal transduction." (PMID 40626019, 2025). "USP7 regulates ferroptosis of tumor cells by deubiquitination and stearoyl-CoA desaturase (SCD)." (PMID 40959280, 2025). "In addition, our analysis of HNSC data from TCGA revealed that both SREBF1 and SCD were overexpressed in tumor tissues." (PMID 40712780, 2025). "In the PPAR signaling pathway, the upregulation of PPARγ and its target gene FABP4, along with the significant downregulation of lipid synthesis enzyme SCD, reveals that EA-2 may remodel tumor cell lipid metabolism by activating the PPARγ pathway." (PMID 40906079, 2025). "Recent studies have found that lipid metabolism pathways in GCSCs are significantly upregulated compared to those in differentiated GC cells, and stearoyl-coa-desaturase (SCD1), an enzyme that regulates the production of tumour lipid ROS, has the highest expression level." (PMID 38166927, 2024). "In this study, a novel nomogram was established by integrating the risk score of four genes (SCD, ALDH1A1, NARS2, and NFXL1), age, Gleason score, and tumor stage, each of which was an independent prognostic factor according to the multivariate Cox regression analysis." (PMID 39335669, 2024). "SCD plays a different role dependent on the cell lineage and tumor contexts." (PMID 39543650, 2024). "The requirement of these FAs as raw materials is higher in tumor cells than in normal cells, which may explain the high expression of SCD in tumor cells." (PMID 38184562, 2024). "Stearoyl-CoA desaturase 1 (SCD1), a rate-limiting enzyme, is involved in the conversion of saturated fatty acids into monounsaturated fatty acids (MUFAs), and it is a key indicator of the tumor microenvironment." (PMID 39126035, 2024). "Furthermore, in a BLCA xenograft model, the inhibition of SCD resulted in substantial suppression of tumor progression, underscoring its potential as a therapeutic target in BLCA management." (PMID 39075554, 2024). "Pharmacological inhibition of SCD showed promising anti-tumor potential in preclinical models." (PMID 39337514, 2024). "This suggests that the promotive effects of SCD expression on PRAD progression may lead to the activation of immune cells in the tumor microenvironment." (PMID 39351232, 2024). "Consequently, the enhanced mitochondrial function and increased levels of SCD induced by CES1 activation promote tumor growth and potential chemoresistance (left)." (PMID 36472914, 2023). "Nevertheless, the lipid signaling–driven pathways that trigger SCD activation in tumor cells remain unclear." (PMID 36472914, 2023). "SCD-1 inhibition can decrease cell viability and inhibit tumor growth 52-54." (PMID 37151873, 2023). "Interestingly, in an SW1 melanoma mouse model, treatment with the SCD inhibitor A939572 inhibited tumor growth but promoted a substantial increase in lung metastases." (PMID 37373069, 2023).